SOD1 (superoxide dismutase 1)
Diseases named in the same sentence as SOD1 in open-access papers (continued):
Sharing a sentence is not in itself a finding about the gene and the disease.
amyotrophic lateral sclerosis (continued). "Mutations in SOD1, associated with the progressive neurodegenerative disorder Amyotrophic Lateral Sclerosis (ALS), cause misfolding and aggregation of the mutant SOD1 (mSOD1) protein." (PMID 24691167, 2014). "Similar effect can be observed in the case of Amyotrophic Lateral Sclerosis: SOD1 has the highest betweenness centrality, followed by VCP and DCTN1 with almost twice as much lower betweenness." (PMID 25528190, 2014). "Transplantation of glial-rich neural progenitors has been demonstrated to attenuate motor neuron degeneration and disease progression in rodent models of mutant superoxide dismutase 1 (SOD1)-mediated amyotrophic lateral sclerosis (ALS)." (PMID 25254338, 2014). "The major aggregating proteins in amyotrophic lateral sclerosis (ALS) are superoxide dismutase 1 (SOD1), TDP-43 (TARDBP) and FUS." (PMID 25358814, 2014). "For example, SAM supplementation in a transgenic mouse model (SOD1-G93A) of amyotrophic lateral sclerosis (ALS) delayed the onset of motor neuron pathology." (PMID 25071843, 2014). "For example, the Cu/Zn superoxide dismutase type-1 (SOD-1) mouse model was developed in order to further understand the etiology and pathogenesis of a subtype of amyotrophic lateral sclerosis." (PMID 23730296, 2013). "Five to 10% of cases of amyotrophic lateral sclerosis are familial, with the most common genetic causes being mutations in the C9ORF72, SOD1, TARDBP and FUS genes." (PMID 23228179, 2013). "As such, we have examined the trophic and proliferative effects of Shh supplementation or Shh antagonism in embryonic spinal cord cell cultures derived from wildtype or G93A SOD1 mice, a mouse model of amyotrophic lateral sclerosis." (PMID 24119209, 2013). "The levels of p67phox were also found to be increased in spinal cord extracts from transgenic superoxide dismutase 1 (SOD1) mice, a genetic animal model of amyotrophic lateral sclerosis." (PMID 24379900, 2013). "In particular, these include models of amyotrophic lateral sclerosis, i.e., the SOD-1-G93A and A315T-TDP-43 strains (Jackson Laboratory, Bar Harbor, ME, USA)." (PMID 23730296, 2013). "To determine, when, how, and which neurons initiate the onset of pathophysiology in amyotrophic lateral sclerosis (ALS) using a transgenic mutant sod1 zebrafish model and identify neuroprotective drugs." (PMID 23281025, 2013). "The SOD1 database converge structural and functional analyses of SOD1; it is a vast resource for the molecular analysis of amyotrophic lateral sclerosis, which allows the user to expand his knowledge on the molecular basis of the disease." (PMID 24312616, 2013). "Most cases of ALS are sporadic; only 5-10% have genetic origin (familial Amyotrophic Lateral Sclerosis - fALS), and only approximately 20% of the fALS cases have mutations in Cu/Zn superoxide dismutase (SOD1)." (PMID 24312616, 2013). "Amyotrophic lateral sclerosis (ALS), partly caused by the mutations and aggregation of human copper, zinc superoxide dismutase (SOD1, EC 1.15.1.1), is a fatal degenerative disease of motor neurons." (PMID 23755211, 2013). "Superoxide dismutase 1 (SOD1) aggregation is one of the pathological markers of amyotrophic lateral sclerosis (ALS), a fatal neurodegenerative disorder." (PMID 24048249, 2013). "Most directly, mutations of the antioxidant superoxide dismutase 1 (SOD1) cause amyotrophic lateral sclerosis (ALS), although this may reflect effects on aggregation rather than oxidation state." (PMID 23797088, 2013). "Amyotrophic lateral sclerosis (ALS), partly caused by the mutations and aggregation of human copper, zinc superoxide dismutase (SOD1), is a fatal degenerative disease of motor neurons." (PMID 23755211, 2013). "Unfortunately, there is no guarantee of such convergence, as the literature on the superoxide dismutase (SOD1) transgenic mouse model of amyotrophic lateral sclerosis (ALS) demonstrates." (PMID 23522086, 2013).
amyotrophic lateral sclerosis (continued). "Research and key discoveries in the field of amyotrophic lateral sclerosis (ALS) have exponentially increased since the announcement in 1993 of the first ALS-causing mutations in the gene for the well-studied antioxidant enzyme Cu,Zn superoxide dismutase (SOD1)." (PMID 23316357, 2012). "For example, a mutant SOD1 transgene that was flanked by loxP sites was used to construct a model for amyotrophic lateral sclerosis (ALS), which was crossed with a P0-Cre driver line." (PMID 21572998, 2011). "Overexpression of mutant copper/zinc superoxide dismutase (SOD1) in rodents has provided useful models for studying the pathogenesis of amyotrophic lateral sclerosis (ALS)." (PMID 21943126, 2011). "Classically used as a model for amyotrophic lateral sclerosis (ALS), transgenic rats expressing the mutated form of the human superoxide dismutase 1 (hSOD1G93A showing a toxic gain of function) are characterized by excitotoxic insults and increased nitroxidative stress." (PMID 21489258, 2011). "Cu/Zn-superoxide dismutase (SOD1) is a ubiquitous enzyme and has been linked to amyotrophic lateral sclerosis (ALS), also known as Lou Gehrig's disease." (PMID 22216152, 2011). "Expression of peroxiredoxin 6 is also increased in a mutant SOD1 mouse model of amyotrophic lateral sclerosis." (PMID 21385431, 2011). "Mutations in the human copper, zinc superoxide dismutase (SOD1) gene are responsible for approximately 2–5% of amyotrophic lateral sclerosis (ALS), an adult-onset neurological disease characterized by loss of motor neurons in the spinal cord as well as brainstem and motor cortex." (PMID 21152319, 2010). "However, more than 140, mostly missense, mutations in the SOD1 gene cause aggregation of the affected protein in familial forms of amyotrophic lateral sclerosis (ALS)." (PMID 20399791, 2010). "To address this, we determined the cryo-electron microscopy structure of the complex between a monoclonal antibody, 19A9, and Cu/Zn-superoxide dismutase (SOD1), a protein associated with canine degenerative myelopathy (DM), which is related to human amyotrophic lateral sclerosis." (PMID 42084503, 2026). "Exposure of a pathogenic β6/β7 loop neo-epitope has been proposed to contribute to the pathogenesis of misfolded Cu/Zn superoxide dismutase (SOD1) in amyotrophic lateral sclerosis (ALS) by mediating early events in its noxious structural transformation and prion-like activity." (PMID 41967177, 2026). "Unlike well-documented mutant SOD1 pathology underlying neuron death in inherited forms of amyotrophic lateral sclerosis (fALS) these alterations are not driven by SOD1 gene mutations, but rather non-genetic alterations to wild-type SOD1." (PMID 40563111, 2025). "Notably, in amyotrophic lateral sclerosis (ALS), preclinical studies suggest that XN can help preserve motor neurons, even in the presence of SOD1 gene mutations." (PMID 39942798, 2025). "Notable examples are HD, caused by an expansion in the huntingtin gene (HTT), and certain familial forms of amyotrophic lateral sclerosis (ALS) that are considered monogenic, associated with mutations in SOD1 (superoxide dismutase), TARDBP (Transactive response DNA-binding protein), or FUS." (PMID 39857412, 2025). "Combining transcranial focused ultrasound, intravesical microbubbles (MBs), and calcium phosphate lipid nanoparticles to deliver superoxide dismutase 1 (SOD1) antisense oligonucleotide to the brains of amyotrophic lateral sclerosis transgenic mice significantly enhanced delivery efficiency." (PMID 40933610, 2025). "Indeed, SOD1 and glutathione peroxidase (GPx) are diminished in the plasma of both familial and sporadic amyotrophic lateral sclerosis patients." (PMID 39446794, 2024).
amyotrophic lateral sclerosis (continued). "However, the mutation in one of the antioxidant enzymes, namely superoxide dismutase-1 (SOD-1) caused Amyotrophic Lateral Sclerosis (ALS), a rapidly progressive neurological disease with the loss of motor neurons that consequently resulted in muscle denervation, atrophy, and paralysis." (PMID 39796008, 2024). "This is particularly evident in the context of the neurodegenerative disease amyotrophic lateral sclerosis (ALS) where ubiquitous over-expression of mutant SOD1 in transgenic mice creates an elevated requirement for copper, and while peripheral tissues are able to meet this demand, the CNS does not." (PMID 39164165, 2024). "We are also interested in the effect of Sparcl1 fusion on known aggregation-prone proteins in the field of neurodegenerative diseases, such as amyloid β in Alzheimer’s disease, α-synuclein in Parkinson’s disease, huntingtin protein in Huntington’s disease, and SOD1 in amyotrophic lateral sclerosis." (PMID 38474544, 2024). "Specifically, superoxide dismutase 1 protein, known to play a major role in the antioxidant response and to be involved in the development of neurodegenerative diseases such as amyotrophic lateral sclerosis (ALS), was found to be significantly upregulated in treated animals." (PMID 38560579, 2024). "None of the MFN2-amyotrophic lateral sclerosis patients tested positive for the pathogenic C9orf72 gene expansion, nor did they exhibit mutations in the SOD1 gene or the known mutational hotspots of the TARDBP (exon 6) and FUS (exons 13-14-15) genes." (PMID 39315308, 2024). "On the other hand, astrocytes expressing mutant SOD1 (copper–zinc superoxide dismutase) release elevated levels of EVs containing mutant SOD1, which can transfer to cultured neurons and induce motor neuron death, suggesting a role for EVs in amyotrophic lateral sclerosis pathogenesis." (PMID 39000150, 2024). "Indeed, intramuscular injection of Pgk1 was shown to significantly reduce or delay neuromuscular junction (NMJ) denervation in Rtn4al-overexpressing Amyotrophic lateral sclerosis (ALS)-like zebrafish and SOD1-mutated ALS-like mice, leading to improved muscle contraction and mobility." (PMID 39409082, 2024). "Its effectiveness was shown through the inhibition of tunicamycin-induced protein aggregation in the hippocampal cell line HT22 and the spontaneous protein aggregation of mutant canine superoxide dismutase 1, akin to human amyotrophic lateral sclerosis, in Neuro2a cells." (PMID 38474354, 2024). "Mutations in SOD1 cause amyotrophic lateral sclerosis (ALS) through gain-of-function effects, yet the mechanisms by which misfolded mutant SOD1 (mutSOD1) protein impairs human motor neurons (MNs) remain unclear." (PMID 37776851, 2023). "Finally, we applied this system as an in vitro model to study the pathophysiology of Amyotrophic Lateral Sclerosis (ALS) and found a decrease in neuromuscular coupling and muscle contraction in co-cultures with MNs harboring ALS-linked SOD1 mutation." (PMID 36866276, 2023). "For example, SOD1 conversion to the amyloid state may lead to the development of amyotrophic lateral sclerosis in humans." (PMID 37958507, 2023). "We selected SOD1 because a strong proportion of non-idiopathic Amyotrophic Lateral Sclerosis (ALS) cases are caused by widely varied mutations to the SOD1 gene." (PMID 35419562, 2022). "Further, SOD1, C9orf72, and SMN1 have been identified as causative genes for amyotrophic lateral sclerosis and spinal muscular atrophy, in which the viability of spinal motor neurons is decreased, and treatment strategies targeting these genes are under development." (PMID 35743104, 2022). "The alteration in the D-loop methylation pattern has been observed in the spinal cord and skeletal muscle cells of human-SOD1 transgenic amyotrophic lateral sclerosis (ALS) mice and in the peripheral blood of patients with both familial and sporadic forms of ALS." (PMID 35628202, 2022).
amyotrophic lateral sclerosis (continued). "For instance, superoxide dismutase (Sod1) was found to be less expressed in 4-week mice and represents a connecting hub of two pathways related to nervous system function in line with its implication in amyotrophic lateral sclerosis (ALS)." (PMID 36448997, 2022). "For example, in a study with amyotrophic lateral sclerosis, both sensory and motor neurons connected with intrafusal fibers accumulating misfolded SOD1 protein were reported to be responsible for the degeneration of annulospiral endings, loss of motor control, and ataxia." (PMID 35370570, 2022). "G93A is an amyotrophic lateral sclerosis (ALS)-associated mutation that does not affect SOD1’s enzymatic activity." (PMID 33859191, 2021). "CTIF also shares a domain with inclusion bodies containing the SOD1 mutant G93A, which is a histologic feature of amyotrophic lateral sclerosis; thus, CTIF may be related to occurrence and development of this disease." (PMID 34239534, 2021). "In the context of amyotrophic lateral sclerosis (ALS), aggregates of superoxide dismutase 1 (SOD1) have been associated with widespread mitochondrial dysfunction and mitochondrial membrane perturbation, as mitochondrial defects have been observed in tissues from ALS patients." (PMID 33791300, 2021). "SOD1 is one of the major antioxidant enzymes and its presence significantly delayed the onset of signs of motor impairment and prolonged the survival of mice suffering from Amyotrophic Lateral Sclerosis (ALS)." (PMID 34834320, 2021). "Genetic disturbances of SOD1 lead to motor neuron disease, amyotrophic lateral sclerosis (ALS)." (PMID 33917579, 2021). "Most cases of amyotrophic lateral sclerosis are sporadic (SALS), and approximately 5–10% represents the familial form of the disease (familial amyotrophic lateral sclerosis (FALS)), in which 20% have a SOD1 gene mutation." (PMID 33802349, 2021). "Sarm1 deletion was beneficial in the TDP-43Q331K model of amyotrophic lateral sclerosis-frontotemporal dementia, but had no significant impact on axonal loss or clinical course of mutant SOD1 model of amyotrophic lateral sclerosis." (PMID 32584865, 2020). "Furthermore, in the SOD1 (G93A) transgenic mice model of amyotrophic lateral sclerosis (ALS), NLRP3 activation was predominantly detected in degenerating neurons of the anterodorsal thalamic nucleus." (PMID 33328988, 2020). "Similarly, CX3CR1 knockout also accelerates disease progression in the G93A mutant Cu, Zn-superoxide dismutase (SOD1) mouse model of amyotrophic lateral sclerosis." (PMID 32410624, 2020). "Amyotrophic lateral sclerosis (ALS) can be familial or sporadic, leading to neurodegeneration of motor neurons in the CNS; a wide range of genetic mutations can induce this neurodegeneration, including the SOD1 gene, which codes for superoxide dismutase." (PMID 32210766, 2020). "Noted examples include ɑ-Synuclein Lewy bodies in Parkinson’s disease, Tau neurofibrillary tangles in Alzheimer’s disease, Superoxide dismutase 1 (SOD1)-mediated aggregates in Amyotrophic Lateral Sclerosis, and mutant Huntingtin protein aggregates in Huntington’s disease." (PMID 32998777, 2020). "Furthermore, we found that S100A4 was significantly up-regulated in astrocytes and microglia in the spinal cord of a transgenic rat SOD1-G93A model of amyotrophic lateral sclerosis." (PMID 31623154, 2019). "Amyotrophic lateral sclerosis (ALS) is a devastating and chronic neurodegenerative disease, characterized by the selective upper and lower motor neuron loss, while about 20–25% of ALS cases are due to different mutations in the SOD1 gene." (PMID 31134076, 2019). "In addition, amyotrophic lateral sclerosis (ALS), which is a degenerative disorder characterized by pathologic hallmark mutant superoxide dismutase 1 activation and aggregation, could be treated by ADSC-Exos." (PMID 31391108, 2019).
amyotrophic lateral sclerosis (continued). "It was shown that microglia uniformly downregulate their homeostatic signature genes, such as Sall1, Pu.1, Tmem119, Cx3cr1, and P2ry12/13 and upregulate risk genes for AD, such as Apoe and Trem2, in mouse models for aging, AD (5XFAD and APP-PS1), and amyotrophic lateral sclerosis (ALS) (SOD1)." (PMID 30108586, 2018). "Several genes have been linked to the onset of amyotrophic lateral sclerosis (ALS, OMIM # 105400), including SOD1, C9ORF72, TARDBP, and FUS, though roughly 80% of cases are of unknown etiology." (PMID 29776328, 2018). "The well-established link between SOD1 and human disease is typified by the development of amyotrophic lateral sclerosis (ALS), a neurodegenerative disease characterized by the progressive loss of motor neurons in the corticospinal tract involving the brain, brainstem, and spinal cord." (PMID 28956814, 2017). "In familial amyotrophic lateral sclerosis (ALS), a neuromuscular disorder characterized by the loss of motor neurons, cortex and upper and lower spinal cord, mutations of Cu, Zn superoxide dismutase 1 (SOD1) have been shown to contribute to the clinical manifestations of ALS." (PMID 27442895, 2017). "As for amyotrophic lateral sclerosis, Nrf2 induction should be assessed in non-SOD1 models." (PMID 28820437, 2017). "In addition, exosomal markers have been found to be associated with amyloid plaques in Alzheimer’s disease (AD) and in vitro models of Amyotrophic Lateral Sclerosis have revealed that misfolded SOD1 transmission can also occur via released exosomes." (PMID 27221146, 2016). "Amyotrophic lateral sclerosis (ALS) or Lou Gehrig’s disease is a rapidly progressive fatal neurological disease with unclear etiology, although mutations in copper/zinc superoxide dismutase (SOD1) are often associated with this disease." (PMID 28536625, 2016). "The genetic and acquired modifications of Cu, Zn-superoxide dismutase (SOD1), a key antioxidant enzyme whose mutations have been linked to the autosomal dominant familial form of amyotrophic lateral sclerosis (ALS), may represent a reference model for this hypothesis." (PMID 26907355, 2016). "Finally, superoxide dismutase 1 (SOD1) aggregations are present in amyotrophic lateral sclerosis (ALS)." (PMID 26881043, 2016). "EVs have been suggested as potential carriers in the intercellular delivery of misfolded proteins associated to neurodegenerative disorders, such as tau and Aβ in AD, α-synuclein in Parkinson’s disease (PD), SOD1 in amyotrophic lateral sclerosis (ALS) and huntingtin in Huntington’s disease (HD)." (PMID 25741766, 2015). "SOD1 (also known as Cu/Zn-SOD) is ubiquitously expressed, localized in the cytoplasm, nucleus and mitochondrial intermembrane space and has been linked to human diseases such as amyotrophic lateral sclerosis." (PMID 26588782, 2015). "Previous studies of spinal motoneurons in the SOD1 mouse model of amyotrophic lateral sclerosis have shown alterations long before disease onset, including increased dendritic branching, increased persistent Na+ and Ca2+ currents, and impaired axonal transport." (PMID 25914627, 2015). "Inhibition of PTEN may also be a promising target in amyotrophic lateral sclerosis (ALS), a well-studied degenerative motor neuron disease that that can be linked to inactivating mutations of the Cu/Zn superoxide dismutase SOD1." (PMID 24744697, 2014). "Noting the similarity of these symptoms to those of Amyotrophic Lateral Sclerosis (ALS) model mice and fish, we asked if mutations in gdf6a would enhance the phenotypes observed in the latter, i.e. in zebrafish over-expressing mutant Superoxide Dismutase 1 (SOD1)." (PMID 24586579, 2014). "The most studied amyloid proteins are Aβ and tau in Alzheimer`s disease (AD), α-synuclein in Parkinson`s disease (PD), superoxide dismutase 1 (SOD1) in amyotrophic lateral sclerosis (ALS), and polyglutamine-rich huntingtin fragments in Huntington`s disease (HD)." (PMID 23340381, 2013).